KEAP1 (kelch like ECH associated protein 1)
Diseases named in the same sentence as KEAP1 in open-access papers (continued):
Sharing a sentence is not in itself a finding about the gene and the disease.
tumor (continued). "Additionally, we observed that tumours recovered by Keap1α-Restored cells were smaller than those recovered by Keap1−/− cells." (PMID 36142252, 2022). "KEAP1 mutation frequently occurs in non-small cell lung cancers like lung adenocarcinoma (LUAD) and lung squamous cell carcinoma (LUSC), which is significantly associated with aggressive tumor growth, resistance to available therapies, and poor prognosis." (PMID 36264074, 2022). "Additionally, CORM-3 exhibits a tumor suppressor effect on TSCC by activating the Keap1/Nrf2/HO-1 antioxidant pathway." (PMID 36158873, 2022). "Then, xenograft tumours were subjected to histopathological examination by routine haematoxylin–eosin staining, followed by immunohistochemical staining with antibodies against Keap1 and PTEN." (PMID 36142252, 2022). "Mechanistically, TRIM15 directly targeted Keap1 by ubiquitination and degradation, the principal regulator of Nrf2 degradation, leading to Nrf2 escaping from Keap1-mediated degradation, subsequently promoting antioxidant response and tumor progression." (PMID 35534896, 2022). "The opposite effects of two different subtypes of Keap1 and their differential expression proportions in distinct tissues may be an axiomatic reason why Keap1 plays dual tumour-promoting and tumour-suppressing roles in different tissues." (PMID 36142252, 2022). "The nuclear factor Keap1-Nrf2 pathway can promote tumor cell survival in hypoxic conditions." (PMID 34316328, 2021). "Mutations in Kelch-like ECH associated protein 1 (KEAP1) were shown to activate the KEAP1/Nuclear Factor erythroid -related factor 2 (NRF2) pathway and subsequently promote cellular detoxifying and antioxidant activities which contributed to tumor development." (PMID 34071790, 2021). "Recent studies have shown that Keap1 affects tumor malignant behaviors." (PMID 34466284, 2021). "In consequence, targeting PERK in order to eliminate NRF2 signaling seems only a rational option in tumor cells that carry a non-mutated Keap1 gene." (PMID 33441543, 2021). "Finally, symmetric dimethylarginine (SDMA), asymmetric dimethylarginine (ADMA) and phenylalanine were markedly increased in tumor compared to peri-tumoral tissue, but these increases were much less pronounced in tumors from either Keap1-KD or Nrf2-KO mice." (PMID 34526660, 2021). "Moreover, we confirmed the mutation in ARID1A gene (p.R1276∗), ERBB3 (p.S128R), KEAP1 (p.R135H), PALB2 (p.P807S), and NTRK1 (p.Q736X), previously reported by F1CDx, both in the tumor and in the ccfDNAs." (PMID 34178989, 2021). "While tumor samples with STK11 mutations were enriched for negative PD-L1 staining, tumor samples with high PD-L1 expression over 50% were less frequently mutated for STK11 or KEAP1." (PMID 34831355, 2021). "Radiation activated Nrf2 via Keap1 silencing and enhanced the tumor-initiating capability of BCSCs." (PMID 33419140, 2021). "These cells carry an activating mutation in the KRAS oncogene but still exhibit low ROS, because inactivation of the KEAP1 tumor suppressor gene in these cells leads to greater accumulation of NRF2 in the nucleus and increased activation of genes coding for antioxidants." (PMID 34204734, 2021). "As the poor prognosis is recognized in SMARCA4-deficient tumors, the presence of frequent co-mutation with other tumor suppressor genes, such as STK11 and/or KEAP1, further dampens the regrettable overall survival and shortens the progression free survival outcome of the disease." (PMID 34440689, 2021). "Moreover, the protein level of KEAP1 in the nude mice xenograft model was significantly upregulated in the tumor of circKEAP1 overexpression group, which in turn downregulated the protein level of NRF2 and HDAC4." (PMID 34136401, 2021).
tumor (continued). "As the classic anti-oncogene, KEAP1 could inhibit tumor occurrence and metastasis via interacting with oncogene NRF2." (PMID 34900441, 2021). "The present study demonstrated that the KEAP1/NFE2L2/CUL3 mutations might be correlated to the lower immune infiltration and higher tumor mutation burden." (PMID 34617407, 2021). "Thus, compared to WT, the levels of myo-inositol, betaine, AMP, succinate, creatine and NAD were higher in tumor tissue of Keap1-KD mice, whereas the levels of methionine and methionine sulfoxide were lower." (PMID 34526660, 2021). "Notably, outliers with extreme negative BFs in BAGEL2 (red) include genes with known tumor suppressor activity, including KEAP1 and Hippo pathway genes NF2 and KIRREL." (PMID 33407829, 2021). "Consequently, low levels of Keap1 induced by epigenetic promoter silencing should enhance apoptosis escape and survival of BC tumor cells via both Nrf2 and Bcl-2." (PMID 34316328, 2021). "Interestingly, the levels of cystathione were increased in the tumors, and although still increased in tumor compared to peri-tumoral tissue, were lower in tumors from Keap1-KD and higher in tumors from Nrf2-KO mice." (PMID 34526660, 2021). "To sum up, in the upcoming sections of this review, we will describe more in detail the structural elements of the NRF2-KEAP1 pathway, the mechanisms underlying the tumor-suppressive and oncogenic properties of NRF2 and KEAP1 proteins as well as both activators and inhibitors of the NRF2 pathway." (PMID 33808001, 2021). "For an in-depth insight into whether KEAP1 mutation or level of NRF2 activation have a distinct effect on the growth and progression of tumor, however, additional studies are needed for further understanding." (PMID 33477494, 2021). "Overall, most differences in metabolites between tumor and peri-tumoral tissues were enhanced in Keap1-KD mice; however, the magnitude of this enhancement was much more modest in comparison with the magnitude of the differences between tumor and peri-tumoral tissues." (PMID 34526660, 2021). "Nrf2 overexpression or Keap1 knockout can inhibit ferroptosis, accelerate the proliferation of glioma cells, and reduce the survival rate of tumor patients, suggesting a potential target for tumor treatment." (PMID 34421604, 2021). "We also recount events that led to the recognition that NRF2 is frequently upregulated in tumour cells, and describe a wide range of mechanisms that allow it to escape repression by KEAP1, with somatic mutations in NFE2L2, KEAP1 and CUL3 being the best characterized examples." (PMID 33276631, 2020). "NRF2 in combination with its own negative regulator, Kelch-like ECH-associated protein 1 (KEAP1), has become the center of a debate regarding whether NRF2 suppresses the tumor promotion or, conversely, exerts pro-oncogenic functions." (PMID 32106613, 2020). "Finally, we discuss topics that warrant further investigation into the KEAP1/NRF2 pathway’s role in tumor progression." (PMID 33080927, 2020). "However, a recent study on tumor tissue from 1,391 NSCLC patients using next-generation sequencing, reported KEAP1 mutations in 157 patients (11.3%) and identified up to 134 different mutations." (PMID 32327612, 2020).
tumor (continued). "Of note, AEM1 was also able to decrease the NRF2-dependent induction of HMOX1 in H838 and H460 NSCLC cells with LOF mutations of the KEAP1 gene, suggesting that AEM1 might preferentially target tumor cells with constitutive NRF2 activation." (PMID 32106613, 2020). "KEAP1 is a cytoplasmic anchor protein of Nuclear factor erythoid-2-related factor 2 (NRF2), encoded by the NFE2L2 gene, which predominantly acts as a key regulator of antioxidant stress responses also in the context of tumor resistance and progression." (PMID 32971994, 2020). "Co-occurring KEAP1 and phosphatase and tensin homolog (PTEN) inactivation represent an immunologically “cold” tumor while concurrent mutations in KEAP1 and STK11 leads to absence of pro-cancerogenic M2 macrophages." (PMID 33194652, 2020). "The first transcript was linked to KEAP1 (Kelch‐like ECH‐associated protein 1), which, through its link to oxidative stress regulating genes, such as glutamate–cysteine ligase and glutathione reductase, is considered as a tumor suppressor gene." (PMID 32821278, 2020). "Notably, cluster 1 had a stronger immunosuppressive tumor microenvironment (TME) and a higher mutation frequency than cluster 2, especially the mutant genes, such as Kelch-like ECH-associated protein 1 (KEAP1) and toll like receptor 4 (TLR4)." (PMID 32445554, 2020). "Additionally, TrkB-mediated PI3K/AKT activation was shown to suppress the expression of Runx3 and Keap1 tumor suppressors that are commonly downregulated in malignant tumors." (PMID 32340410, 2020). "Unlike mutations in NFE2L2, somatic mutations in KEAP1 were found to be distributed throughout the gene, which represents the mutational pattern associated with tumour suppressor genes." (PMID 33276631, 2020). "The tumor sizes of the A549 cell line stably transfected with the R320Q KEAP1mutant were significantly larger than those of the A549 cell line stably transfected with WT KEAP1." (PMID 32576270, 2020). "The co-occurrence of KEAP1 and KRAS mutations suggests that KEAP1 mutations either affect NRF2 activity differently than KRAS-stimulated overexpression of NRF2, or are affecting other signalling pathways that are beneficial to the tumour." (PMID 33276631, 2020). "In the present study, we used targeted next-generation sequencing for mutation analysis of primary tumor tissues from 50 patients metastatic RCC, and we detected Nrf2 gene mutation in 5 patients, Keap1 gene mutation in 11 patients, and VHL gene mutation in 35 patients." (PMID 31752777, 2019). "Furthermore, immunohistochemical analysis demonstrated that overexpression of miRNA-421 reduced KEAP1 expression in tumours." (PMID 31659154, 2019). "One important observation here is the reduced immune infiltrates in Redox tumors, which suggests that NFE2L2/KEAP1 signaling may lead to tumor evasion of immune surveillance programs." (PMID 31395880, 2019). "Many tumor types with NRF2 activation (either NRF2 or KEAP1 non-synonymous mutation) show increased frequency of mutations." (PMID 30150714, 2018). "In addition to an impairment of the GSK3β-directed β-TrCP pathway, aberrant accumulation of Nrf2 is augmented by inhibition of the Keap1-based proteasome-mediated degradation in Nrf1α−/−-derived tumor cells." (PMID 30562963, 2018). "In addition, several other proteins, such as DPP3 (dipeptidyl-peptidase 3) or WTX (Wilms tumor gene on X chromosome), can interact with Keap1 and modulate the Nrf2-Keap1 pathway." (PMID 29438305, 2018). "Moreover, as a result of Keap1 disruption, constitutive Nrf2 activation can lead to drug and radiation resistance in tumours." (PMID 30513925, 2018). "Keap1 immunoreactivity was observed in the cytoplasm of tumor cells." (PMID 28061437, 2017).
tumor (continued). "Pre-NACT nuclear Keap1 expression was also connected with better tumor differentiation (p = 0.029)." (PMID 29348788, 2017). "It has been shown that Keap1 could inhibit tumor metastasis by targeting Nrf2/S100P pathway in NSCLC cells." (PMID 27579312, 2016). "Based on our observed inverse relationship between UHRF1 and Keap1 levels in cell lines, we sought to determine whether this was relevant in patient tumour samples." (PMID 26497117, 2016). "Moreover, p62 phosphorylation through an mTOR-dependent mechanism increases its affinity to Keap1, leading to persistent Nrf2 activation to enhance tumor growth." (PMID 27200299, 2016). "As a result, p62 would inactivate normal Keap1 protein synthesized from the Keap1-allele without the mutation, leading to a vicious circle of Nrf2 activation in the tumour cells." (PMID 27345495, 2016). "As expected, double-immunofluorescence analysis with anti-p62 and anti-S349-phosphorylated p62 or anti-p62 and anti-Keap1 antibodies revealed extensive co-localization of S349-phosphorylated p62 and Keap1 in the p62-positive aggregate structures in HCV-positive HCC tumour cells." (PMID 27345495, 2016). "On the basis of this evidence, we hypothesized that specific inhibitor(s) of the interaction between S349-phosphorylated p62 and Keap1 would recover the ability of Keap1 to bind to Nrf2, and possibly function as an anti-tumour drug for HCC." (PMID 27345495, 2016). "In this study, to understand the role of Keap1 and pNrf2 in HCC and to investigate the association between their expression and prognosis of HCCs, we analyzed their expression status in paratumor and tumor and elucidate their clinical implication." (PMID 27650414, 2016). "KEAP1 inactivating and NRF2 activating mutations have been identified in human tumor biopsies." (PMID 25897966, 2015). "The frequency of KEAP1 promoter hypermethylation varies among tumor types." (PMID 26247201, 2015). "Therefore, we treated WT and Keap1-/- MEFs, as well as the panel of 20 human tumor lines, with RTA 405 and measured the protein levels and activities of NRF2, BCL2 and IKKβ." (PMID 26301506, 2015). "Moreover, in human tumor biopsies, IKKβ protein levels are inversely correlated with KEAP1/CUL3 levels." (PMID 26301506, 2015). "The results above indicate that high basal NRF2 activity levels, reflective of KEAP1 loss or mutation, do not protect tumor cells from RTA 405-mediated growth inhibition." (PMID 26301506, 2015). "Kelch-like ECH-associated protein 1 (Keap1) inhibits nuclear factor erythroid 2-related 2 (NEF2L2; also named NRF2)-induced cytoprotection and has been hypothesized to represent a candidate tumor suppressor." (PMID 24137397, 2013). "Indeed, increased expression and activity of NRF2, resulting from mutations in KEAP1 and/or NRF2, have been observed in various tumor cells, including skin, breast, prostate, lung, head/neck, and endometrium." (PMID 22476201, 2012). "Aberrant promoter methylation of KEAP1 was detected in 53% of tumor tissues and 25% of normal mucosae from 40 surgical CRC specimens, indicating that cancerous tissue showed increased methylation of the KEAP1 promoter region, conferring a protective effect against cytotoxic anticancer drugs." (PMID 22325485, 2012). "As mutations in NRF2-regulating tumor suppressors KEAP1 and CUL3 are not confined to specific hotspot regions, our findings advocate for a multimodal profiling approach combining somatic mutation assessment with protein or transcriptomic evaluation of NRF2 targets." (PMID 41771797, 2026). "Indeed, alterations in KEAP1 and/or STK11, which are especially frequent in KRAS-mutated tumours, promote an immunosuppressive tumour microenvironment, enriched in suppressive myeloid cells and depleted in CD8+ cytotoxic T cells, but with relative sparing of CD4+ effector T cells." (PMID 40849356, 2025).
tumor (continued). "Here we provide proof of concept that non‐BRAF mutated SCC of the thyroid may develop from preexisting PTC, involving homozygous inactivation of several tumor suppressor genes, including KEAP1, which has previously been reported to be oncogenic in lung adenocarcinoma and lung SCC." (PMID 40600748, 2025). "While this procedure provides an elaborate comparison of immune cell infiltrations into WT and KEAP1-KO tumor tissues, there remains a possibility that both tumors residing bilaterally might affect the immune cell conditions mutually or might influence in a specific direction." (PMID 41035689, 2025). "However, the mechanisms of resistance to anti-PD-1/PD-L1 remain unclear, and more studies are needed to characterize the immune microenvironment of KEAP1-mutant tumours." (PMID 40647497, 2025). "Importantly, this unbiased screening identified several hits that positively regulate PRMT5 expression, including oncoproteins such as HRAS and BRAF, whereas tumor suppressors like KEAP1 were identified as top-scoring hits that negatively regulate PMRT5 levels." (PMID 40091834, 2025). "Notably, activation of NRF2 occurs in several malignancies through a variety of mechanisms, including mutations in KEAP1 or NRF2 that disrupt their interaction, epigenetic changes that influence NRF2 and KEAP1 expression, and chronic stress within the tumor microenvironment." (PMID 40678507, 2025). "Similarly, the efficacy of metabolic interventions in KEAP1-mutant tumours may be modulated by the gut microbiome, while microbiome-based interventions might help restore immune function in JAK1/2-mutant cases." (PMID 40277912, 2025). "Consequently, sustained or high-level inhibition of KEAP1 may inadvertently contribute to tumor progression, particularly in the setting of established malignancies." (PMID 40646550, 2025). "Thus, our model provides a mechanistic explanation for the clinical observation that KEAP1 mutant NSCLC tumours respond poorly to G12Ci drugs, and argues that alternative treatment strategies would be more appropriate for patients who present with KEAP1 or NFE2L2 mutant NSCLC tumours." (PMID 40890297, 2025). "However, when tumor cells are exposed to elevated levels of ROS, Keap1 becomes inactivated." (PMID 40530331, 2025). "Furthermore, the Keap1/NRF2/ARE signaling pathway plays a critical role in tumor cell drug resistance, and PVT1 may further promote the development of resistance by regulating this pathway." (PMID 40258841, 2025). "In summary, our single-cell analysis demonstrates that combining DRP-104 with anti-PD1 may alter the functionality and transcriptional state of Keap1 mutant tumor–infiltrating CD4 and CD8 T cell populations, driving them from an exhausted program toward a more functional effector/memory state." (PMID 38536921, 2024). "Furthermore, the dysregulation of PD-L1, coupled with reduced KEAP1-mediated regulation, could contribute to tumor progression and poor survival outcomes." (PMID 38413563, 2024). "Importantly, KEAP1 overexpression enhances the anti-tumor therapeutic efficiency in mice." (PMID 38413563, 2024). "ADAR1 deficiency resulted in tumor survival suppression, apoptosis, and oxidative stress (with enhanced intracellular ROS accumulation, reduced intracellular GSH content and SOD activity and increased MDA content) of HCC cells by mediating Keap1-Nrf2 signaling." (PMID 38468359, 2024). "Taking into account the well-known role of the KEAP1/NRF2 pathway in chemotherapy resistance, pharmacological tests were also performed to investigate whether KEAP1 suppression had an impact on SCLC as a molecular marker to predict tumor cell response to cisplatin and etoposide agents." (PMID 38791966, 2024).